KRTDAP (keratinocyte differentiation associated protein)
Description:
May act as a soluble regulator of keratinocyte differentiation. May play an important role in embryonic skin morphogenesis.
Synonyms: KDAP; UNQ467
Tractability: Antibody: UniProt places it where antibodies can reach, with high confidence; UniProt predicts a signal peptide or a membrane-spanning region; its Gene Ontology location is reachable by antibodies, with medium confidence.
Gene: Protein-coding gene on chromosome 19 (35,487,324 to 35,495,558, reverse strand). Ensembl gene ENSG00000188508.
Subcellular location: Secreted
Pathways (Reactome):
Developmental Biology: Differentiation of Keratinocytes in Interfollicular Epidermis in Mammalian Skin
Gene Ontology:
Biological process: epidermis development
Cellular component: extracellular region; lamellar body
Genetic constraint (gnomAD): Loss-of-function variants: 12 observed, 17.67 expected, observed/expected ratio (o/e) 0.68, 90% interval 0.43 to 1.1. The upper end of that interval is the gene's LOEUF score, 1.1, which puts it in group 4 of 6, group 1 being the genes least tolerant of losing a copy. Missense variants: 110 observed, 120.27 expected, observed/expected ratio (o/e) 0.91, 90% interval 0.78 to 1.07. Synonymous variants: 50 observed, 49.54 expected, observed/expected ratio (o/e) 1.01, 90% interval 0.8 to 1.28.
Homologues: Orthologues: chimpanzee KRTDAP (99% identical), macaque KRTDAP (99% identical), dog KRTDAP (89% identical), rabbit KRTDAP (83% identical), pig KRTDAP (82% identical), guinea pig KRTDAP (67% identical), rat Krtdap (60% identical), mouse Krtdap (55% identical).
Diseases named in the same sentence as KRTDAP in open-access papers:
KRTDAP is named in the same sentence as 8 diseases in open-access papers, as found by Europe PMC text mining. Sharing a sentence is not in itself a finding about the gene and the disease. The quoted sentences say what the papers report.
adenosquamous carcinoma (1 paper, 2021). A carcinoma composed of malignant glandular cells and malignant squamous cells. "Since the pathological tumor tissue was adenosquamous carcinoma, we observed several keratins, including KRT1, KRT6B, KRTDAP, and KRT10, in C5." (PMID 34326696, 2021).
Atrophy (1 paper, 2024). Any weakening or degeneration, especially through lack of use. "Notably, two atrophy-linked switch-like genes in the vagina that we identified, KRTDAP and KRT1, are crucial for the differentiation of epithelial cells in the vagina 48,49." (PMID 39315271, 2024).
melanoma (1 paper, 2022). A malignant, usually aggressive tumor composed of atypical, neoplastic melanocytes. "The role of KRTDAP is mainly in keratinocyte differentiation; therefore, this may indicate that metastatic melanoma tissue is less differentiated compared to primary lesions." (PMID 36553569, 2022). "Genes, such as members of the keratin family (KRT17, KRTDAP, KRT6B, KRT14, KRTAP13-2) are expressed more in primary tumor, possibly indicating the differentiated status of less advanced cancers, or this could be a disruption in their normal expression by melanoma processes." (PMID 36553569, 2022).
metastatic tumor (1 paper, 2022). "On the other hand, KRTDAP was found to have higher expression in primary tumor compared to metastatic tumor." (PMID 36553569, 2022).
KRTDAP also shares sentences with these, for which no sentence is quoted: tumor (4 papers); cancer (1); cervical cancer (1); squamous carcinoma (1).